OR8D4 (olfactory receptor family 8 subfamily D member 4)
Description:
Odorant receptor.
Synonyms: OR11-275
Tractability: Antibody: UniProt places it where antibodies can reach, with medium confidence; UniProt predicts a signal peptide or a membrane-spanning region; its Gene Ontology location is reachable by antibodies, with medium confidence.
Gene: Protein-coding gene on chromosome 11 (123,902,167 to 123,909,229, forward strand). Ensembl gene ENSG00000181518.
Subcellular location: Cell membrane
Pathways (Reactome):
Sensory Perception: Expression and translocation of olfactory receptors
Gene Ontology:
Molecular function: olfactory receptor activity; G protein-coupled receptor activity
Biological process: G protein-coupled receptor signaling pathway; sensory perception of smell; detection of chemical stimulus involved in sensory perception of smell
Cellular component: plasma membrane; membrane
Genetic constraint (gnomAD): Missense variants: 326 observed, 352.6 expected, observed/expected ratio (o/e) 0.92, 90% interval 0.84 to 1.01. Synonymous variants: 125 observed, 128.47 expected, observed/expected ratio (o/e) 0.97, 90% interval 0.84 to 1.13.
Homologues: Orthologues: chimpanzee OR8D4 (97% identical), macaque OR8D4 (92% identical), pig OR8D4 (86% identical), rat Or8d4 (84% identical), mouse Or8d4 (84% identical), dog OR8D4 (82% identical), guinea pig OR8D4 (82% identical), tropical clawed frog or5dd2b (44% identical). Paralogues in human: OR8A1 (64% identical), OR8D1 (64% identical), OR8G1 (60% identical), OR8G3 (59% identical), OR8D2 (59% identical), OR8G5 (59% identical), OR8B3 (58% identical), OR8B2 (57% identical), OR8B8 (57% identical), OR8G2P (57% identical), OR8B4 (55% identical), OR8B12 (55% identical), and 84 more.
Diseases named in the same sentence as OR8D4 in open-access papers:
OR8D4 is named in the same sentence as 1 disease in open-access papers, as found by Europe PMC text mining. Sharing a sentence is not in itself a finding about the gene and the disease. The quoted sentences say what the papers report.
systemic lupus erythematosus (1 paper, 2023). An autoimmune multi-organ disease typically associated with vasculopathy and autoantibody production. "OR8D4 has been encountered as a risk gene of systemic lupus erythematosus." (PMID 37672513, 2023).